CD4 (CD4 molecule)
Diseases named in the same sentence as CD4 in open-access papers (continued):
Sharing a sentence is not in itself a finding about the gene and the disease.
Autoimmunity (continued). "Naturally occurring CD4+CD25+ regulatory T cells (nTreg) play an indispensable role in preventing autoimmunity mostly via Foxp3-dependent transcription." (PMID 25880134, 2015). "Th1, Th17, and IL-22-producing CD4 T cells in psoriasis and autoimmunity have recently been supposed." (PMID 26339139, 2015). "In general, the role of DCs during the development of autoimmunity is to induce autoreactive CD4+ and CD8+ proinflammatory T cell differentiation rather than immunosuppressive Treg development or autoreactive T cell anergy." (PMID 24877157, 2014). "Previous studies indicated that CD11a overexpression by CD4+ T cells affects the development of autoreactivity in vitro and autoimmunity in vivo." (PMID 25414732, 2014). "The in situ pathogenicity of GRP78 autoimmunity in smokers is also strongly supported by finding this stress response protein is an autoantigen of CD4 T-cells in these subjects, especially among those with emphysema." (PMID 25216103, 2014). "In this model CD8+ T cells mediate biliary ductular damage, whereas CD4+ T cells mediate induction of colon-specific autoimmunity." (PMID 25133396, 2014). "For example, the presence of CD4+ regulatory T cells plays an important role in the control of the onset of autoimmunity." (PMID 24586733, 2014). "CD4+ T-cells are a vital component of the immune system, as they protect against cancer, infection, and play a role in autoimmunity." (PMID 25538703, 2014). "Here, for the first time, we characterized CD4-PPARγKO mice to investigate the intrinsic role of PPARγ in T cells and autoimmunity related to TFH cells and GC reaction." (PMID 24921943, 2014). "Natural CD4+CD25+ Treg (nTreg) prevent autoimmunity and contribute to the induction of transplant tolerance." (PMID 24847323, 2014). "Effects of Al on autoimmunity, oral tolerance, CD4+ and CD8+ expression, hypersensitivity, and erythrocyte immune function are suggestive of its immunotoxicologic activity." (PMID 25243176, 2014). "Since the CD4 T cells are central in the origin and regulation of autoimmunity, emphasis has been placed on the characterization of Th subsets and their possible roles in the inflammatory autoimmune process." (PMID 24905409, 2014). "Our results demonstrated that CD4+ T cell intrinsic defects are responsible for attenuated autoimmunity in Mst1−/− mice and provide further evidence for an essential and non-redundant role of Mst1 expressed in the CD4+ T cell compartment in EAE progression." (PMID 24852423, 2014). "Like Foxp3KO mice, CTLA4KO mice die of CD4 driven autoimmunity so in reality CTLA4 blockade can only be partial in human patients." (PMID 24782861, 2014). "The wild-type CD4+ T cells were able to prevent the induction of autoimmunity as manifested by a significant reduction in titers of IgG1 and IgG2a ANoA following Hg challenge." (PMID 25122007, 2014). "Treg cells are CD-4 and Fox-P3 positive and are known to play an important role in immune surveillance and self-tolerance and in suppressing autoimmunity." (PMID 24194760, 2013). "While the exogenous or endogenous antigen(s) causing PFAPA remain unidentified, a decrease in CD4+/CD25+ lymphocytes, which maintain peripheral tolerance to the immune response and regulate natural immune responses to prevent autoimmunity, has been reported." (PMID 22940910, 2013). "To determine if reduced IL-2 responsiveness is a common feature of autoimmunity, we measured pSTAT5 in response to IL-2 in CD4+CD25hi T cells of T1D, MS and SLE patients." (PMID 24376757, 2013). "The CD4+ and CD8+ T cells have been implicated in inflammatory response, apoptosis, and autoimmunity leading to type 1 DM." (PMID 24348714, 2013). "The Th17 CD4+ helper T cell subset (defined by the secretion of IL-17) are considered to play an important role in promoting inflammation and autoimmunity." (PMID 23382807, 2013).
Autoimmunity (continued). "In a model of autoimmunity, other authors proposed that DCs were central to Treg inhibition in vivo and attenuated priming of CD4-helper cells." (PMID 22890822, 2013). "Naive CD4+ T cells differentiate into T helper cells 1 (Th1) and 2 (Th2) for inflammatory response and autoimmunity." (PMID 24348714, 2013). "Increasing evidence points to the distinct roles of different CD4+ T cell subsets in anti-microbial immune response, allergies, tolerance, autoimmunity, and inflammation." (PMID 23531279, 2013). "This thymic TR deletion results in lethal autoimmunity, in contrast to peripheral TR deletion through CD4-CreERt2." (PMID 24115907, 2013). "The mechanism underlying these effects involves not only CD4+ FoxP3− effector T cells (Teff cells) but also CD4+ FoxP3+ regulatory T cells (Treg cells), which prevent GVHD and autoimmunity, produced by the allotransplanted thymus." (PMID 23762092, 2013). "IFN-γ inhibits induction of iTreg from CD4+ T cells, whereas other report IFN-γ is key to induction of CD4+CD25− T cells to iTreg that suppress autoimmunity in IFN-γ deficient mice." (PMID 23935597, 2013). "A study on a thymectomised mouse model showed that CD4+CD25+ Tregs can prevent autoimmunity and allergy." (PMID 23680475, 2013). "Another possibility was that TR2 was not ablated in the T cell subset required for development of autoimmunity, but several studies indicated that both CD4+ and CD8+ T cells are responsible for the autoimmune phenotype in absence of TGF-β signalling." (PMID 24115907, 2013). "Our study reveals that a UPK3A peptide can induce a peptide-specific CD4+ T cell autoimmunity that mediates painful bladder dysfunction in mice." (PMID 23977210, 2013). "Conceivably, innate immune danger signals, such IL-15, serve to boost the protective responses to pathogens that are otherwise faintly stimulatory to CD4+ T cells, while preventing unwanted systemic stimulation of unrelated CD4+ T cells and thus autoimmunity." (PMID 23028916, 2012). "Many studies demonstrated that the proliferative CD4+ T-cell response to GAD65 (one of the pancreatic β-cell antigens) was a relevant marker for cellular autoimmunity in T1D." (PMID 22754354, 2012). "CD4+CD25high regulatory T-cells play an important role in the establishment of the immunological self tolerance and thereby, preventing autoimmunity." (PMID 22898564, 2012). "The thymus is known to produce a regulatory CD4+ T-cell subset (Treg), fundamental for preventing autoimmunity, currently best identified by expression of the forkhead box P3 transcription factor (FoxP3)." (PMID 22590644, 2012). "In humans and the NOD mouse, a spontaneous model for T1D, β cell autoimmunity is viewed as a chronic inflammatory response mediated by autoreactive CD4+ and CD8+ T cells." (PMID 23251685, 2012). "IL-6 is also involved in autoimmunity by altering the balance of Th17 cells by inducing the differentiation of Th17 cells from naïve CD4+ T cells." (PMID 23133751, 2012). "CD4+ CD25high regulatory T-cells (Tregs) play an important role in the establishment of immunological self tolerance and thereby, in the prevention of autoimmunity." (PMID 22748016, 2012). "Naturally occurring CD4+CD25+ FOXP3+ regulatory T-cells (nTREG) are a subpopulation of CD4 T-cells capable of suppressing the activation and expansion of T-effector cells, thereby inhibiting the onset of autoimmunity." (PMID 23118856, 2012). "The autoimmunity in the LGs of the γDKO mouse was accompanied by an increase in CD4+, CD8+ T- and B-cell infiltration with aging from ages 8 to 16 weeks, an increase in M3R autoantibodies, and a concomitant decrease in EGF concentration in tears." (PMID 23116218, 2012). "The seminal experiments by Sakaguchi in 1995 identified that immunosuppressive CD4+ CD25(IL-2Rα)+ T cells protected mice from autoimmunity mediated by CD4+ CD25– T cells." (PMID 23060881, 2012).
Autoimmunity (continued). "CD4+ CD25+ FOXP3+ regulatory T cells are a population of CD4 T cells crucial for the regulation of immune responses and in preventing autoimmunity and chronic inflammation." (PMID 22586481, 2012). "The forkhead box transcription factor, Foxp3, is master regulator of the development and function of CD4+CD25+ T regulatory (Treg) cells that limit autoimmunity and maintain immune homeostasis." (PMID 22247766, 2012). "Islet transplantation provides a “cure” for type 1 diabetes but is limited in part by recurrent autoimmunity mediated by β cell-specific CD4+ and CD8+ T cells." (PMID 23251685, 2012). "The adoptive transfer of CD4+CD25+ nTreg prevents the development of such organ-specific autoimmunity." (PMID 21647403, 2011). "CD4-DNTGFβRII mice are phenotypically normal until 6∼8 weeks of age, when they start developing spontaneous wasting syndrome and autoimmunity and die around 12∼16 weeks of age, mainly due to colitis." (PMID 22194977, 2011). "Because absence of TGF-β from birth always correlates with development of autoimmunity, we evaluated the effects of aging on surface inflammation in CD4-DNTGFβRII aged 4, 8 and 14 weeks and compared them to WT mice of similar ages." (PMID 22194977, 2011). "Regulatory T cells suppress the responses of alloreactive or self-reactive CD4+ T cells and are supposed to maintain immunologic self-tolerance or control autoimmunity." (PMID 21658226, 2011). "For instance, CD8+ and CD4+ T cells play important roles in hepatocellular damage, antiviral defenses (to hepatitis viruses), or autoimmunity." (PMID 21197451, 2011). "The transfer of CLN CD4+ T cells from wild type mice treated with nasal anti-CD3 protected IL-27R−/−/lpr recipients from the development of fatal autoimmunity (compare blue and red lines)." (PMID 21886804, 2011). "More recently, another phenotype of CD4+ T helper cells, so-called Th17 cells have been implicated in the development of EAE and other autoimmune disorders." (PMID 20356357, 2010). "Although potentially autoreactive memory-like CD8+ T cells generated in a lymphopenic environment are subject to the mechanisms of peripheral tolerance, they can induce autoimmunity in the presence of antigen-specific memory-like CD4+ T helper cells." (PMID 20856822, 2010). "The important role of Foxp3+CD4+CD25+ Treg cells in immune homeostasis is that it controls autoimmunity throughout life." (PMID 20618924, 2010). "Both cytokines are implicated in APC function, which is in turn a prerequisite for induction of auto-reactive CD4+ T cells and autoimmunity." (PMID 20370892, 2010). "Recently, CD4+IL-17A+ T helper 17 (Th17) cells were identified and reported in several diseased states, including autoimmunity, infection and various peripheral nervous system tumors." (PMID 21060663, 2010). "Th17 cells are CD4+ cells that produce interleukin 17 (IL-17) and are potent inducers of tissue inflammation and autoimmunity." (PMID 19457253, 2009). "Accumulating evidence supports CD4+ CD25high regulatory T cells playing an essential role in controlling and preventing autoimmunity." (PMID 19302705, 2009). "Pro-inflammatory factors associated with autoimmunity, such as IL-1, IL-6, and TNF-α, also can inhibit CD4+CD25high regulatory T cell function." (PMID 19046457, 2008). "Further, cross-linking of MCP (CD46) with the TCR on naïve CD4+ T cells induces regulatory T cells, which are critical in the balance between autoimmunity and tolerance." (PMID 17878210, 2008). "CD4+CD25+Foxp3+ regulatory T (Treg) cells are believed to play an important role in suppressing autoimmunity and maintaining peripheral tolerance." (PMID 18304352, 2008). "It is now generally accepted that CD4+CD25+ Treg cells play a major role in the prevention of autoimmunity and pathological immune responses." (PMID 15743476, 2005). "It has recently been shown that CD4+CD25+ regulatory T cells involved in the control of autoimmunity can express CD134." (PMID 15899047, 2005).
Autoimmunity (continued). "aureus and its PGN translocation may drive anti-CD4 autoimmunity and hinder immune recovery in PWH on suppressive ART, highlighting S." (PMID 41930968, 2026). "This study investigates whether antibody binding promotes PLA2R internalization and lysosomal processing to enhance MHCII-mediated antigen presentation and CD4+ T cell activation, thereby contributing to the perpetuation of autoimmunity in PMN." (PMID 41328348, 2026). "Besides, C acnes can activate autoimmunity that induces differentiation of CD4+ T cells into Th17 cells and promotes secretion of inflammatory factors." (PMID 39620488, 2025). "We thus hypothesized that some circulating autoreactive CD4 T cells derive from an exacerbated clonal expansion in the tissue during active autoimmunity." (PMID 39880819, 2025). "Th17 cells, a subset of CD4+ T cells, are known for their role in autoimmunity and inflammation." (PMID 40658180, 2025). "Also, consistent with a protective function in autoimmunity, the level of regulatory CD4+ T cells was increased." (PMID 39835539, 2025). "Focusing on CD4+ Te cells, these cells play pivotal roles in orchestrating immune responses and not only are they important in protective immunity, but also have a key role in the development of autoimmunity." (PMID 39894902, 2025). "Additionally, understanding CD4+ T-cell resistance to other immunosuppressive therapies during transplantation and autoimmunity is crucial for disrupting immune persistence." (PMID 40634636, 2025). "Thus, CD4+Notch2+Foxp3lo T cells function as immunoregulatory CD4+ T cells that play a central role in recovery from inflammation during autoimmunity." (PMID 40702356, 2025). "The Nobel laureate Shimon Sakaguchi and colleagues observed that thymectomized mice had decreased numbers of CD5hi CD4+ T cells, and that transfer of this population could prevent the development of autoimmunity." (PMID 41366167, 2025). "It is unclear whether this signature reflects autoimmunity and CNS-inflammation and can support trans-endothelial migration of CD4+ TH across the blood–brain barrier." (PMID 40537813, 2025). "Together, these data strongly suggest that the dysfunction of CD4 Treg cells may contribute to the severity of inflammation and autoimmunity in SLE, leading to a less controlled and more aggressive disease course." (PMID 40744996, 2025). "Importantly, UMCD6 is known to block T-cell-dependent autoimmunity through effects on differentiation of effector CD4+ T cell subsets, opening a new approach to cancer immunotherapy that will suppress rather than instigate immune-adverse related events." (PMID 39996744, 2025). "Regulatory T cells (Tregs) are a distinct population of CD4+ lymphocytes which express the transcription factor forkhead homeoboxprotein-3 (Foxp3), are essential for maintaining immune homeostasis, and contribute to the prevention of autoimmunity." (PMID 40631071, 2025). "Future studies examining broader functional, replicative, and transcriptional programs in CD27−CD28− CD4+ T cells will be essential to define the role of senescent CD4+ T cells in autoimmunity and chronic infection, and to inform strategies for modulating their activity." (PMID 41235706, 2025). "Overall, uncovering the inherent vulnerabilities of stem-like CD4+ T cells may be key to effectively targeting them in autoimmunity and alloimmunity." (PMID 40634636, 2025). "Although these TRM-like signatures described in the literature present overlap with classical TRM CD4 T cells in healthy tissues, it is still difficult to make the distinction between tissue residency and chronic activation, especially during cancer, autoimmunity, and virus immune response." (PMID 39880819, 2025). "By depleting the CD25+ CD4+ population (now known as Treg cells) and transferring the remaining T cells to athymic mice, they could observe the development of autoimmunity." (PMID 41366167, 2025).
Autoimmunity (continued). "The study integrated peripheral CD4+ T cells from healthy individuals, autoimmunity patients (MS, SLE and myasthenia gravis) and other conditions and created a machine learning model to predict T cell identity, representing a promising step towards integrating results across studies." (PMID 40534591, 2025). "To determine whether autoreactive CD4+ Teff cells can be reprogrammed into bona fide Tregs for mitigating established autoimmunity, we developed an approach to achieve stable demethylation of Treg identity genes in CD4+ Teff cells." (PMID 40762956, 2025). "To determine whether CD4+ TIA cells may contribute to the etiology of autoimmunity, we first assessed whether they are present in autoimmune settings." (PMID 38838013, 2024). "In addition to innate immune sensing of pathogens, Ku70 recognizes accumulated cytoplasmic DNA in CD4+ T cells and drives CD4+ T cell activation, promoting aging-related autoimmunity, further implicating a role for Ku70 beyond DNA damage repair." (PMID 38277448, 2024). "A specific subset of DCs, plasmacytoid DCs (pDCs), are associated with autoimmunity and IFN-I and IL-12 secretion, which facilitates the polarization of CD4+ T cells into Th1 helper T cells and the consequent accumulation of CTL CD8+ T cells involved in anti-tumor response." (PMID 38791916, 2024). "Regulatory T cells (Tregs), a subset of CD4+T cells marked by the expression of the transcription factor forkhead box protein 3 (Foxp3), are pivotal in maintaining immune equilibrium and preventing autoimmunity." (PMID 39290699, 2024). "CD4+ Tregs expressing the transcription factor Foxp3 is required for peripheral immunological tolerance (regulation of autoreactive immune cells); deletion of Foxp3 on CD4+ regulatory cells leads to multiorgan autoimmunity and malfunction of Tregs are related to the alteration of the Foxp3 gene." (PMID 38213874, 2024). "ALKBH5 modulated CD4+ T cells to respond and enhance autoimmunity." (PMID 39229575, 2024). "The expansion of MBZ and simultaneous stimulation with pathogen- or damage-associated molecular patterns (PAMPs/DAMPs) and self-antigen is related to presentation of self-antigen, activation of self-reactive CD4+ T helper cells, secretion of autoantibodies, and development of autoimmunity." (PMID 38406025, 2024). "As revealed by evidencing studies, NLRC3 increases many genes related to the activation of Th1/Th17/T cells, such as Ifng, Tnf, Il17f, Il17a, and Tbx21; also, study reveals that Nlrc3 expression in T cells inhibits autoimmunity as well as CD4+ T cell responses specific for virus." (PMID 38436712, 2024). "To test the hypothesis that NOX2 deficiency in T cells contributed to autoimmunity in SLE, we crossed the Cybbfl/fl with CD4-Cre MRL.Faslpr strains to generate a cohort of experimental Cybbfl/fl CD4-Cre–positive mice and Cre-negative Cybbfl/fl controls." (PMID 39042716, 2024). "discussed nicely the role of bystander CD4 T cells in infection, autoimmunity, and cancer." (PMID 39669576, 2024). "Overall, these results indicated that RNF213 might serve a critical role in autoimmunity through regulating the differentiation of CD4+ T cell subpopulations." (PMID 39013878, 2024). "Notably, elevated numbers of memory CD4+ T-cells observed in autoimmune conditions like psoriasis suggest a potential role in promoting autoimmunity." (PMID 38396174, 2024). "CD4+ T cells are also key players in the induction and pathogenesis of autoimmunity." (PMID 39302339, 2024). "Regulatory CD4+ T cells (Tregs) are pivotal for inhibition of autoimmunity." (PMID 38607233, 2024). "In addition, IL-15 has also been shown to play a central role in CD4+ T cell proliferation, Th17 effector function, T helper cell differentiation, and neuronal-autoimmunity." (PMID 37809060, 2023).